MMP3 (matrix metallopeptidase 3)
Diseases named in the same sentence as MMP3 in open-access papers (continued):
Sharing a sentence is not in itself a finding about the gene and the disease.
tongue cancer (2 papers, 2024). A malignant neoplasm affecting the tongue. "As for SCC-9, MMP3 upregulation and formation of MMPs complexes lacking proteolytic activity are expected to be the causal agents for tongue cancer cells migration restriction." (PMID 38740853, 2024).
uveitis (2 papers, 2016 to 2024). An inflammatory process affecting a part of or the entire uvea. "In this study, we provide important evidence for the contribution of MMP-3 to acute retinal inflammation, using a mouse model of endotoxin-induced uveitis (EIU)." (PMID 27809288, 2016). "We investigated whether MMP-3 contributes to acute inflammation in the eye using the endotoxin-induced uveitis (EIU) model." (PMID 27809288, 2016). "In this study, we aimed to quantitatively assess the levels of MMP-3 and TIMP-1 in the aqueous humor (AH) of ARN patients, using virus-negative uveitis (UV) patients as a control group." (PMID 39723192, 2024). "Our quantitative analysis, conducted on a large sample size of VZV-induced ARN patients, revealed significantly elevated levels of MMP-3 and TIMP-1 in the aqueous humor compared to virus-negative uveitis cases presenting with retinal inflammation." (PMID 39723192, 2024).
viral myocarditis (2 papers, 2021 to 2023). Myocarditis that is caused by an infection with a viral agent. "For instance, GBE can alleviate viral myocarditis by inhibiting matrix metalloproteinase‐3 (MMP‐3), a protein reported to mediate immune cell migration and cytokine secretion." (PMID 36419341, 2023).
Achilles tendinitis (1 paper, 2018). "In addition, the local injection of SIM/PMSs into the tendons of collagenase-induced Achilles tendinitis rat models suppressed pro-inflammatory cytokines (MMP-3, COX-2, IL-6, TNF-α, and MMP-13)." (PMID 29534523, 2018). "In order to investigate the in vivo anti-inflammatory effects of SIM/PMSs on collagenase-induced Achilles tendinitis models, we monitored the mRNA levels of both pro-inflammatory cytokines (MMP-3, COX-2, IL-6, TNF-α, and MMP-13) and anti-inflammatory cytokines (IL-4, IL-10, and IL-13)." (PMID 29534523, 2018).
Achilles tendon injuries (1 paper, 2010). "It was found that variants within COL5A1, tenascin C and matrix metalloproteinase 3 (MMP3) gene was associated with increased risk of Achilles tendon injuries in general." (PMID 21144004, 2010).
Acidosis (1 paper, 2021). Abnormal acid accumulation or depletion of base. "Acidosis increased the expression of MMP3 and MMP9, enzymes which break down ECM components and accordingly, there were decreased levels of both collagen II and aggrecan recorded under acidic conditions." (PMID 33824228, 2021).
adhesive capsulitis (1 paper, 2024). "It was demonstrated that the mRNA expression of MMP-2 in samples from patients with adhesive capsulitis was found more often than MMP-1 or MMP-3." (PMID 38381214, 2024).
age-related macular degeneration (1 paper, 2016). Age-related loss of vision in the central portion of the retina (macula), secondary to retinal degeneration. "In addition, significantly increased MMP-3 mRNA levels are detected in RPE/choroid samples of age-related macular degeneration (AMD) patients, indicating its importance in ocular inflammatory processes." (PMID 27809288, 2016).
aggressive periodontitis (1 paper, 2015). "Moreover, MMP3 rs35068180 polymorphism might be associated with a lower risk of aggressive periodontitis (AgP) in Asians (allelic genetic model: OR = 0.66, 95% CI: 0.48–0.91, Pheterogeneity = 0.945), and CP in Caucasians and Brazilians." (PMID 26123623, 2015).
aging (1 paper, 2022). A developmental process that is a deterioration and loss of function over time. "The increase of MMP-1 and MMP-3 leads to excessive degradation of collagen, which is an essential factor leading to skin aging." (PMID 36364921, 2022).
alcohol (1 paper, 2017). "We investigated 13 SNPs to explore the relation of polymorphisms of the genes MMP-3 and MMP-8 to alcohol-induced ONFH risk in Chinese males." (PMID 28445942, 2017).
ameloblastoma (1 paper, 2024). The most common odontogenic tumor, arising from the epithelial component of the embryonic tooth and usually affecting the molar-ramus region of the mandible or maxilla. "Therefore, this study suggests MMP-3 as an invasive marker for ameloblastoma." (PMID 38226014, 2024). "MMPs are well-studied in the case of ameloblastoma, however there is not much data on MMP-3 and most of the reported literature is on MMP-2, -7, and -9." (PMID 38226014, 2024).
ampullary cancer (1 paper, 1996). "The results implicate MMP2, MMP3 and TIMP1 in the invasive phenotype of pancreatic and ampullary cancer." (PMID 8611434, 1996).
aortic valve disease (1 paper, 2011). "Our results show that elevated pressure induces a gene expression pattern in cells that is considerably similar to that seen in aortic valve disease, in terms of altered expression of ECM proteins (MMP-1, MMP-3) and proinflammatory cytokines (IL-1β, IL-6)." (PMID 21876831, 2011).
apical periodontitis (1 paper, 2025). "Some SNPs in the MMP-2 and MMP-3 genes have been studied, testing the hypothesis that these SNPs could be associated with increased susceptibility to apical periodontitis (AP), thereby contributing to different stages of the inflammatory process, bone remodeling, and tissue regeneration." (PMID 40725414, 2025). "Studies observing a significant increase in the expression levels of MMP-1, MMP-2, MMP-3, MMP-7, MMP-9, and TIMP 1 could be related to an individual predisposition to apical periodontitis (AP)." (PMID 40725414, 2025).
Arterial thrombosis (1 paper, 2025). The formation of a blood clot inside an artery. "In contrast to the studies mentioned, our results may support the assumption that the MMP-3 rs3025058 6A6A genotype (vs. 5A5A) tends to decrease the risk of arterial thrombosis (OR = 0.400, 95% CI 0.155–1.031, p = 0.058)." (PMID 40724896, 2025). "Moreover, MPN patients carrying the MMP-1 rs19799750 1G2G genotype (vs 2G2G) tended to have an increased risk of arterial thrombosis (p = 0.059), while the MMP-3 rs3025058 6A6A genotype (compared to 5A5A) showed a tendency towards decreased arterial thrombosis (p = 0.058)." (PMID 40724896, 2025). "On the contrary, the MMP-3 rs3025058 showed a tendency for decreased arterial thrombosis." (PMID 40724896, 2025).
Atherosclerotic lesion (1 paper, 2021). A lesion associated with atherosclerosis, a multifactorial and multipart progressive disease manifested by the focal development within the arterial wall of lesions, that ranges from the development of a fatty streak, plaque progression, and plaque disruption.
autoimmune myocarditis (1 paper, 2021). Autoimmune myocarditis is an autoimmune disease that affects the heart. "Increased activation of MMPs such as MMP-3 and MMP-9 were also observed in experimental mouse autoimmune myocarditis." (PMID 34680049, 2021).
brain glioma (1 paper, 2021). A malignant glioma that involves the brain. "There has been some evidence suggesting the importance of MMP3 in the pathogenesis of brain gliomas." (PMID 33608513, 2021).
bronchopulmonary dysplasia (1 paper, 2022). Bronchopulmonary dysplasia is a chronic respiratory disease that results from complications related to lung injury during the treatment of infant acute respiratory distress syndrome in low-birth-weight premature infants or from abnormal lung development in older infants. "In a rat model of bronchopulmonary dysplasia (BPD), montelukast treatment inhibited the expression of hyperoxia-induced mesenchymal markers, such as collagen I (Col I), metalloproteinase-1 (MMP-1), MMP-3, TGF-β1, and Smad3, in lung tissues by inactivating the TGF-β1/Smad signaling pathway." (PMID 35517780, 2022).
burn (1 paper, 2024). A traumatic injury involving interruption of tissue cohesiveness that results from exposure to caustic chemicals, extreme heat, extreme cold or excessive radiation. "In short, the effect of skin burn on patients is to regulate the expression of immune-related genes UPP1, MMP1, MMP3, and skin regeneration-related gene DPT, which may be the key target for the treatment of skin burn." (PMID 36103997, 2024).
cardiac hypertrophy (1 paper, 2022). "The DEGs associated with cardiac hypertrophy were screened via bioinformatics analysis, and eight hub genes were identified, including Akt1, Lox, Timp1, Col1al, Spp1, Ccnd1, Mmp3, and Egfr, which might be a new target for the identification of cardiac hypertrophy." (PMID 36046382, 2022).
cataract (1 paper, 2018). Partial or complete opacity of the crystalline lens of one or both eyes that decreases visual acuity and eventually results in blindness. "Compared with the cataract group, the concentration of IL-8, MMP-2, MMP-3, MMP-9, TGFβ-1, TGFβ-3, and TNF-α was significantly increased in subjects with JIAUwG or JIAUwoG." (PMID 29675026, 2018).
cerebral aneurysm (1 paper, 2014). "We have previously found that TNF-α can activate a number of pro-inflammatory and matrix remodeling genes in cerebral vascular smooth muscle cells directly implicated in cerebral aneurysm formation, including: MMP-3, MMP-9, MCP-1, VCAM-1, and IL-1β; and IL-1β, VCAM-1 and MCP-1." (PMID 24739142, 2014).
cervical spondylosis (1 paper, 2012). "These TIMP protein findings are not in agreement with those reported by Le Maitre and colleagues; however, they do corroborate those by Kanemoto and colleagues where 78.1% of cervical spondylosis and 93.3% of lumbar spondylosis specimens were MMP-3 positive and TIMP-1 negative." (PMID 22394620, 2012).
colonic diverticulosis (1 paper, 2023). "This collective elevation in MMP-3 and MMP-9 activity potentially engenders an escalated degradation of basal lamina proteins, thereby establishing a plausible predisposition to colonic diverticulosis." (PMID 38004080, 2023). "Given this intricate relationship between MMPs and colonic diverticulosis, this pilot study sought to investigate whether selected genetic variants in MMP3, MMP9, and MMP12 are associated with the incidence of colonic diverticulosis." (PMID 38004080, 2023).
colorectal adenoma (1 paper, 2006). An adenoma that arises from the colon or rectum. "To explore whether MMP1, MMP3 and MMP7 gene promoter polymorphisms are involved in the early step of colorectal carcinogenesis, we investigated the relation between these polymorphisms and the risk of colorectal adenoma in a case-control study." (PMID 17125518, 2006).
congenital toxoplasmosis (1 paper, 2025). Toxoplasma infection that is present from birth. "Thus, based on previous reports and our findings, it is conceivable that T. gondii-driven repression of MMP3 is partially responsible for reduced EVT invasion activity and pregnancy complications associated with congenital toxoplasmosis." (PMID 41450565, 2025).
corneal disease (1 paper, 2012). "Further, in support of the contribution of IL-17A in the corneal disease that develops in the nude recipients, we measured the number of IL-17A, CCL20, MMP-3 and MMP-9 mRNA transcripts in this tissue." (PMID 22590618, 2012).
cryptococcosis (1 paper, 2025). An acute or chronic, localized or disseminated infection by Cryptococcus neoformans. "In particular, MMP-3 may be involved in CD146 shedding, and studies in patients with cryptococcosis showed high levels of MMP-9 in the cerebrospinal fluid of patients infected with C. neoformans." (PMID 40208055, 2025).
cutis laxa (1 paper, 2016). Cutis laxa (CL) is an inherited or acquired connective tissue disorder characterized by wrinkled, redundant and sagging inelastic skin associated with skeletal and developmental anomalies and, in some cases, with severe systemic involvement. "Levels of dermal expression of MMP-3, MMP-9, and MMP-12 are increased in cutis laxa lesional fibroblasts or lymphocytes and are correlated with the degree of disruption of elastic fibers." (PMID 28116317, 2016).
diabetic neuropathy (1 paper, 2024). A chronic, pathological complication associated with diabetes mellitus, where nerve damages are incurred due to diabetic microvascular injury involving small blood vessels that supply these nerves, resulting in peripheral and/or autonomic nerve dysfunction. "The present study indicates that high MMP-3 is associated with low eGFR, high plasma creatinine, and macroalbuminuria, and that GDF-15 can be a biomarker for diabetic neuropathy in T1D." (PMID 39000435, 2024).
dissection (1 paper, 2014). The separation and isolation of tissues for surgical purposes, or for the analysis or study of their structures. "Therefore MMP-3 and MMP-9 can be considered as common mediators in the pathogenesis of both aortic dissection and atrophic striae." (PMID 24720641, 2014). "Furthermore, increased MMP-3 expression in the PBMC cells of the patients with dissection compared to the annuloaortic ectasia group, apparently contributes to the development of the severe pathologic changes leading to aortic dissection." (PMID 24720641, 2014).
dry eye (1 paper, 2018). "More interestingly, a recent study conducted on the effect of the MK2 inhibitor on a mice model of dry eye showed a suppression of cell apoptosis and a decrease of MMP3 and MMP9 in corneal epithelium." (PMID 30374345, 2018).
ductal carcinoma (1 paper, 2021). "Nevertheless, of the total number of patients analyzed with cancer, we identified that MMP-1 staining intensity and MMP3 staining percentage and intensity were higher in postmenopause patients, in those with positive hormone receptors, and in the histological ductal carcinoma type." (PMID 34445715, 2021).
duodenal ulcer (1 paper, 2010). An ulcer in the duodenal wall. "The combined MMP-3/TIMP-1 genotype as 6A6A/CC had a 3.6-fold (p < 0.05) increased risk of duodenal ulcer in H. pylori-infected female." (PMID 20707923, 2010). "In conclusion, this study provides evidence that host promoter polymorphisms of MMP-3 contribute to increased individual susceptibility to duodenal ulcers in females after H. pylori infection in Taiwan." (PMID 20707923, 2010). "This study discloses the host genotype MMP-3 -1612 as 6A6A, which expresses lower MMP-3 carries a 2.4-fold risk of having duodenal ulcers among females after H. pylori infection (p < 0.05)." (PMID 20707923, 2010). "H. pylori-infected subjects with the MMP-3 6A6A genotype had a 2.4-fold (95% CI: 1.02-5.66) increased risk of duodenal ulcer in females compared to those with the 5A carrier." (PMID 20707923, 2010). "Because TIMP-1 genotypes modulated MMP-3 activity, it was further tested whether the MMP-3-1612/TIMP-1372 Combined genotypes contributed to increased risk of duodenal ulcers in females." (PMID 20707923, 2010). "Moreover, TIMP-1 372, as CC, contributes a higher risk of duodenal ulcers to MMP-3 -1612 6A6A." (PMID 20707923, 2010). "Combining the MMP-3/TIMP-1 genotype as 6A6A/CC, the risk of duodenal ulcer increased up to 3.6 fold (p < 0.05) in H. pylori-infected females." (PMID 20707923, 2010). "However, the exact reason why such a combined MMP-3/TIMP-1 genotype as 6A6A/CC has just an increased risk of duodenal ulcer in H. pylori-infected females, but not in male, remains uncertain." (PMID 20707923, 2010). "The MMP-3 promoter polymorphism, but not the dupA-status, may correlate with susceptibility to duodenal ulcer after H. pylori infection in Taiwanese females." (PMID 20707923, 2010).
E. coli infection (1 paper, 2021). "We demonstrated that meningitic E. coli infection of hBMECs induced the significant upregulation of lncRSPH9-4, which facilitated the barrier disruption of the endothelial cells, probably through lncRSPH9-4/miR-17-5p/MMP3 axis." (PMID 34198485, 2021).
endotoxemia (1 paper, 2016). "The number of leukocytes significantly increased, respectively, by 3- and 2-fold in the vitreous of WT and MMP-3−/− eyes after induction of endotoxemia." (PMID 27809288, 2016). "As such, blocking MMP-3 results in a reduced leukostasis response in the retinal vasculature during endotoxemia." (PMID 27809288, 2016). "As such, MMP-3 deficiency/reduction clearly attenuates LPS-induced hypothermia, supporting a devastating role of MMP-3 in endotoxemia and its contributing inflammatory processes in the CNS." (PMID 27809288, 2016). "Alternatively, also activation of the MAP kinase P38 or ERK pathway after induction of endotoxemia can possibly trigger cytokine-induced MMP-3 transcription/translation." (PMID 27809288, 2016). "Moreover, a trend towards a diminished number of infiltrating vitreous leukocytes at the optic nerve head, a known site for early infiltration, was observed in MMP-3−/− mice, as compared to WT eyes, after induction of endotoxemia." (PMID 27809288, 2016). "However, after induction of endotoxemia, an increment in Mmp3 mRNA levels was observed, especially in the RPE, with a peak at 16 hpi and a decline thereafter." (PMID 27809288, 2016). "Interestingly, pro MMP-3 significantly increased in the vitreous cavity at 8 and 24 hpi by 4.4- and 26-fold respectively, suggesting a translocation of MMP-3 to the vitreous after induction of endotoxemia." (PMID 27809288, 2016).
esophageal adenocarcinoma (1 paper, 2018). A malignant tumor with glandular differentiation arising predominantly from Barrett mucosa in the lower third of the esophagus. "Although our study did not reveal correlation between MMP3–1612 6A/5A, MMP12 -82A/G polymorphisms and RHD in Han population, studies have shown a combined effect of MMP1–1607 1G/2G, MMP3–1612 6A/5A and MMP12-82A/G polymorphisms associated with esophageal adenocarcinoma (EA) risk in Caucasian." (PMID 29458338, 2018).
experimental autoimmune encephalomyelitis (1 paper, 2022). An autoimmune demyelinating disease of the central nervous system that is produced experimentally in animals by the injection of homogenized brain or spinal cord in Freund's adjuvant. "Based upon the preliminary data obtained from the MP4-induced experimental autoimmune encephalomyelitis (EAE) mouse model where gene expression of MMP-3 was spatially associated with the presence of B cell aggregates, here we analyzed the expression pattern of MMP-3 in MS brain tissue." (PMID 36389698, 2022).
follicular thyroid carcinoma (1 paper, 2025). "Molecular research indicated that one of the transmembrane glycoproteins could induce MMPs including MMP3 and participate in carcinoma invasion in follicular thyroid carcinoma." (PMID 40575254, 2025).
gastric diseases (1 paper, 2011). "Our results suggest that curcumin acted both-ways during protection of Hp-infection by eradicating Hp as well as potentially targeting the key molecules (MMP-3 and -9) involved in the Hp-induced gastric diseases." (PMID 21283694, 2011).
hearing loss (1 paper, 2021). "Moreover, the levels of chemokines Fractalkine and MIP1α were similarly elevated in BDBV survivors with hearing loss while levels of sIL6-Ra, MMP-3, and APRIL were reduced." (PMID 34093585, 2021).
hemarthrosis (1 paper, 2021). Bleeding into the joints. "Higher levels of SF MMP-3 and TIMP-1 also associated with the presence of hemarthrosis (moderate or severely blood-stained SF) and the severity of injury." (PMID 33671471, 2021).
hidradenitis suppurativa (1 paper, 2025). A chronic suppurative and cicatricial disease of the apocrine glands occurring chiefly in the axillae in women and in the groin and anal regions in men. "MIR132 heightens inflammation and pain sensitivity, while matrix metalloproteinases (MMPs), specifically MMP-2 and MMP-3, significantly impact the pathogenesis of hidradenitis suppurativa (HS)." (PMID 39940809, 2025).